CXCL12 (C-X-C motif chemokine ligand 12)
Diseases named in the same sentence as CXCL12 in open-access papers (continued):
Sharing a sentence is not in itself a finding about the gene and the disease.
oral cancer (10 papers, 2012 to 2023). "We have previously demonstrated that a stromal cell-derived factor-1 (SDF-1; CXCL12)/CXCR4 system is involved in the establishment of metastasis in oral cancer." (PMID 25536052, 2014). "Notably, blockage of CXCR4 as well as its ligands CXCL12 during oral cancer promotion could be employed as a new therapeutic strategy in future." (PMID 22496601, 2012). "A recent immunohistochemical study has confirmed that this relationship showing a significant relationship between CXCL12 and CXCR4 was found both in potentially malignant lesions and oral cancer." (PMID 24376459, 2013). "Although recently attentions have been paid to the relationship between CXCR4 and oral cancer, until now, no report focuses on the alterations of CXCL12/CXCR4 axis in premalignant stage of oral cancer." (PMID 22496601, 2012).
pituitary adenomas (10 papers, 2012 to 2025). "An activated CXCL12/CXCR4 axis has also been associated with proliferation of pituitary adenomas." (PMID 22349813, 2012). "CXCR4 mRNA is expressed in almost all GH-secreting pituitary adenomas and in the great majority of NFPAs, whilst CXCL12 was identified in about 2/3 of these tumors." (PMID 25484899, 2014). "Another chemokine, CXCL12, was able to induce auto-/paracrine cell proliferation in human pituitary adenomas." (PMID 23946783, 2013). "Overall, these observations imply that CXCL12/CXCR4 axis might play an important biological role in pituitary adenoma as potential growth and angiogenic factor for pituitary cells." (PMID 25484899, 2014). "Indeed, CXCL12 stimulates GH transcription and secretion in both primary rat anterior pituitary cells and the GH-producing pituitary adenoma cell line, GH3." (PMID 25484899, 2014). "Consequently, alterations of the endocrine regulatory pathways due to upregulation of hypothalamic/pituitary CXCL12/CXCR4 axis might lead to the development of pituitary adenomas." (PMID 25484899, 2014). "Finally, the evaluation of CXCR4 and CXCL12 expression in invasive and noninvasive pituitary adenoma specimens, by flow cytometry and immunohistochemical staining, demonstrated that the percentage of CXCR4- and CXCL12-positive cells was significantly higher in invasive pituitary adenomas." (PMID 25484899, 2014). "CXCL12 secretion from CXCR4 expressing cells supports the occurrence of autocrine/paracrine mechanism in GBM CSCs, in human meningioma and pituitary adenoma cells." (PMID 30564115, 2018). "Moreover, interactions between CSCs and tumor microenvironment through secreted CKs (e.g., CXCL12), possibly occurring also in pituitary adenomas, may act as chemoattractant to recruit fibroblasts, endothelial, mesenchymal, and inflammatory cells to the tumor, via CXCR4." (PMID 25484899, 2014). "Both CXCL12 and CXCR4 are constitutively overexpressed in pituitary adenomas and their signalling induces cell survival and proliferation, as well as hormonal hypersecretion." (PMID 25484899, 2014). "For instance, CXCL12-regulated miR-370–3p acts as a tumor suppressor of nonfunctional pituitary adenomas via targeting HMGA2." (PMID 31703640, 2019). "However, such generalized CXCR4 and CXCL12 overexpression in human pituitary adenomas, as compared to normal pituitary, strongly suggests that, in conditions of deregulation, this receptor system could be a relevant factor for pituitary adenoma development and/or progression." (PMID 25484899, 2014). "Interestingly, GH4C1 rat pituitary adenoma cell line expresses CXCR4 but not CXCL12, thus it was proposed as a suitable model to characterize the molecular pathways regulated by this receptor in pituitary adenomas, without the interference of the endogenously released CK." (PMID 25484899, 2014).
preeclampsia (10 papers, 2014 to 2025). Preeclampsia is a hypertensive disorder of pregnancy that is characterized by new-onset hypertension with proteinuria presenting after 20 weeks of gestation, and depending on mild or severe forms may initially present with severe headache, visual disturbances, and hyperreflexia. "It is believed that dysregulation of placental derived vasculogenic and angiogenic substances in maternal blood, such as stromal cell-derived factor-1 (SDF-1/CXCL12) underlie the pathogenesis of preeclampsia." (PMID 35455936, 2022). "We therefore additionally monitored the expression of two key mediators in the placenta from these mice: CXCL10 (originally IP-10) and CXCL12 (originally SDF-1) are both implicated in preeclampsia and in the innate immune response to Toxoplasma gondii." (PMID 30691477, 2019). "CXCL12 is another chemokine strongly linked to preeclampsia and the placental trophoblast response to infection." (PMID 30691477, 2019). "Moreover, polymorphisms in CXCR4 and CXCL12 have been associated with preeclampsia in humans." (PMID 37815869, 2023). "Low expression levels of CXCL12 and CXCR4 in peripheral blood and decidual/placental tissues are associated with miscarriage and preeclampsia in women." (PMID 37815869, 2023). "Increases in maternal blood CXCL12 have been reported in preeclampsia, and correlated with increased syncytiotrophoblast CXCL12 staining and intrauterine growth restriction." (PMID 35455936, 2022). "Low expression of SDF-1α/CXCR4 in placentas of women with preeclampsia appears to confirm the role of CXCL12/CXCR4 in this type of complication in pregnancy." (PMID 27556030, 2016). "Notably, previous studies have shown that decreased ACKR3 expression in placentas and increased CXCL12 levels in blood were observed in pregnant women diagnosed with preeclampsia." (PMID 38300826, 2024). "Further studies will be needed to explore the therapeutic potential of interventions aimed at the CXCL12/CXCR4 axis in pregnancy disorders related to immunological and angiogenic imbalances during early gestation, such as recurrent pregnancy loss and preeclampsia." (PMID 37815869, 2023). "Since CXCL12 is a chemokine known to also activate platelets, preeclampsia onset and progression may correlate with plasma CXCL12 levels and the extent of activated platelets in maternal circulation." (PMID 35455936, 2022). "Besides, mRNA expression and quantification of CXCL12 in preeclampsia placenta were higher compared with those in normal placenta, especially in syncytiotrophoblasts of preeclampsia placenta." (PMID 25485631, 2014). "Numerous studies have demonstrated that patients with severe preeclampsia exhibit elevated plasma levels of various chemokines—CXCL8 (IL-8), CCL2 (MCP-1), CXCL10 (IP10), and CXCL12 (SDF-1)—compared to healthy pregnant women." (PMID 41463301, 2025). "Dysregulation of CXCL12/CXCR4/CXCR7 axis leads to placental dysfunction by attenuating trophoblast invasion and migration, and contributes to pregnancy disorders including preeclampsia, miscarriage, and fetal growth restriction." (PMID 33795831, 2021). "Women with preeclampsia show increased circulating levels of CXCL10, CXCL11, CXCL12, and CXCL3." (PMID 41463301, 2025). "Indeed, accumulating evidence in humans suggests that dysfunction of the CXCL12/CXCR4 axis may be related to pregnancy complications, including miscarriage and preeclampsia." (PMID 37815869, 2023).
angina (9 papers, 2011 to 2025). "The clinical significance of platelets’ increased CXCL12 expression in patients with angina pectoris remains to be clarified." (PMID 37959416, 2023). "Except for a few clinical reports advocating the protective role of CXCL12 on the basis of the clinical finding of decreased serum CXCL12 levels in stable and unstable angina, almost all studies emphasize a proatherogenic role of CXCL12." (PMID 34494495, 2021). "Plasma levels of CXCL12 are decreased in patients with stable and unstable angina compared with healthy controls." (PMID 30210493, 2018). "A study, comparing plasma CXCL12 levels of angina patients with healthy controls, showed decreased levels of CXCL12 in the patient group." (PMID 26257740, 2015). "In contrast, another study observed significantly increased CXCL12 expression on platelets of stable angina patients, compared to healthy controls." (PMID 26257740, 2015). "In contrast, angina patients show increased platelet expression of CXCL12, compared to healthy controls, and plasma CXCL12 levels correlate with platelet activation, suggesting more pro-atherogenic effects of CXCL12." (PMID 26175090, 2015). "CXCL12 thus might have a protective effect in unstable angina through stabilizing the atherosclerotic plaque." (PMID 30210493, 2018). "Patients with unstable angina had even lower CXCL12 levels than those with stable angina." (PMID 26257740, 2015). "Likewise, patients with angina displayed reduced CXCL12 plasma levels compared to healthy controls." (PMID 24966838, 2014). "Therefore, high (local) concentrations of CXCL12 may mediate anti-inflammatory and matrix-stabilizing effects promoting plaque stabilization and may be beneficial in angina pectoris and ACSs." (PMID 24966838, 2014).
astrocytoma (9 papers, 2011 to 2024). "In another study of a mouse model of astrocytoma revealed that SDF-1 (CXCL12) effectively promotes GAM recruitment to the vicinity of the malignancy in a concentration-dependent fashion within the hypoxic TME." (PMID 37153567, 2023). "Other studies inferred that Sp1 may drive CXCL12 expression in human astrocytoma cells, human lung fibroblasts, and rat β-cells." (PMID 36670936, 2022). "The CXCL12/CXCR4 axis has gained increased focus during the recent decade and has been extensively studied in brain tumors (GBM, astrocytoma, medulloblastoma, oligodendroglioma, and oligodendroastrocytoma) due to its key role in the communication of tumor cells with their microenvironment." (PMID 35745762, 2022). "In addition, CXCL11 and CXCL12 were low or absent in the astrocytoma and in the M2 macrophage secretome." (PMID 38472446, 2024). "On the other hand, CXCR4 and CXCL12 expression frequently occurs in GBM proliferating vascular endothelium, but not in endothelial cells from astrocytomas in which proliferation of microvessels is less abundant." (PMID 24904289, 2014).
chronic myelogenous leukemia (9 papers, 2016 to 2024). "In the case of hematological malignancies, contrary to what happens with MSCs, depletion of CXCL12 in BM ECs has been reported to reduce CSCs, as shown in chronic myeloid leukemia." (PMID 33530455, 2021). "Another study reported that the level of CXCL12 in the BM with chronic myelogenous leukemia (CML) was decreased, which impaired the homing efficacy of both exogenous transplanted LSCs and healthy HSCs." (PMID 29740536, 2018). "Likewise, altered cytokine expression such as a decrease of CXCL12 production in the BM of a mouse model of chronic myelogenous leukemia (CML) conferred a growth advantage to leukemia stem cells (LSCs) over normal stem cells." (PMID 34858421, 2021). "Moreover, in a murine model of chronic myeloid leukemia deletion of CXCL12 in MSCs was shown to support the expansion of leukemic stem cells and suppress normal hematopoiesis, while deletion of CXCL12in endothelial cells led to a diminished expansion of leukemic stem cells." (PMID 33878141, 2021). "MSCs mediate protection of chronic myelocytic leukemia (CML) cells from imatinib-induced apoptosis through reducing the activity of caspase-3 and expression of anti-apoptotic protein Bcl-xl via a CXCL12/CXCR4 axis." (PMID 35842634, 2022). "More importantly, when analyzing different cancer cell lines, we found CXCL12 was lowly expressed among most hematopoietic neoplasms, especially in AML and chronic myelocytic leukemia (CML)." (PMID 34327063, 2021).
ischemic cardiomyopathy (9 papers, 2015 to 2022). Ischemic cardiomyopathy is a cardiomyopathy in which a weakness in the muscle of the heart due to inadequate oxygen delivery to the myocardium with coronary artery disease being the most common cause. "The CXCL12 (also known as SDF-1)/CXCR4 axis has been previously reported to be involved in the retention and mobilization of stem cells in the adult ischemic cardiomyopathy, supporting the notion that CXCL12 might have therapeutic potential." (PMID 31029167, 2019).
keloid (9 papers, 2020 to 2026). An irregularly shaped, elevated mark on the skin caused by deposits of excessive amounts of collagen during wound healing. "One study evaluated the expression of circulating fibrocytes and the chemokine CXCL12 in keloid patients to elucidate their role in keloid formation." (PMID 41596210, 2026). "Additionally, the expression level of CXCL12 in keloid tissue (529.3 pg/mL) was also significantly upregulated." (PMID 41596210, 2026). "We identified four subpopulations of endothelial cells in keloid and normal scar tissue by scRNA-seq data: MMP1+ Endo0, FOS + JUN + Endo1, IL6+CSF3+ Endo2, CXCL12 Endo3." (PMID 36082167, 2022).
small cell lung carcinoma (9 papers, 2009 to 2026). Small cell lung cancer (SCLC) is a highly aggressive malignant neoplasm, accounting for 10-15% of lung cancer cases, characterized byrapid growth, and early metastasis. "In small cell lung cancer, CXCL12 induces integrin activation, which results in enhanced adhesion of cancer cells to the extracellular matrix, thereby conferring resistance to chemotherapeutic drugs." (PMID 33514011, 2021). "Small cell lung cancer cell lines present constitutive phosphorylation of STAT3, and in the reference cell lines NCI-H69 and NCI-H82 constitutive phosphorylation was further increased by CXCL12 stimulation." (PMID 19455144, 2009).
thrombosis (9 papers, 2014 to 2024). "Many systemic inflammatory diseases such as rheumatoid arthritis, systemic lupus erythematous, and familial Mediterranean fever have upregulated CXCR4 and/or increased circulating plasma levels of CXCL12, and these conditions also carry a predisposition to thrombosis." (PMID 39062849, 2024). "Several recent studies have associated the inhibition of the CXCR4/CXCL12 axis with a reduction in both arterial and venous thrombus formation, with increased circulating levels of CXCL12 and Pim-1 observed in deep vein thrombosis." (PMID 39062849, 2024). "Appropriately, the overexpression of miR 103a-3p resulted in a reduction of CXCL12 protein levels in the bloodstream and inhibited venous thrombosis in mice, thus providing further support of the concept." (PMID 37954596, 2023). "At the translational level, CXCL12 activity is regulated by microRNAs (miRs) and posttranslational by proteolytic processing with impact on venous thrombosis." (PMID 37954596, 2023). "Beyond the platelet-dependent role of CXCL12 in atherothrombosis, platelets and likely also CXCL12 play an essential role in venous thrombosis." (PMID 37954596, 2023). "Evaluation of plasma from 81 patients with lower-extremity deep vein thrombosis showed a decrease in expression of miR-103-3p and increased expression of chemokine C-X-C motif ligand 12 (CXCL12) that has a target site for this miRNA." (PMID 32443696, 2020). "Circulating levels of miRNA 103a-3p are decreased in individuals with deep vein thrombosis, and CXCL12 is a target of miRNA 103a-3p, which may explain the observed increase in plasma CXCL12 levels in these patients." (PMID 37954596, 2023). "Tinzaparin, a CXCL12 inhibitor, is an FDA-approved drug for the treatment of deep vein thrombosis and pulmonary embolism, which are considered as AADs." (PMID 35347083, 2022). "The baseline levels of IL-6, IL-10, VCAM-1, CCL19, BCA-1, IL-4, E-selectin, fractalkine, CXCL12, and GCP2 were found to differ statistically among the control, arterial thrombosis, AF-related venous thrombosis, and major bleeding groups (p < 0.05)." (PMID 36211709, 2022). "Among them, F2, MMP9, CXCL12, and MET are also the seed nodes in the network cluster analysis and have been shown that they have a multi-dimensional connection with thrombosis." (PMID 34433871, 2021). "In addition, it has been reported that plasma CXCL12 levels were significantly elevated in the blood of patients with TAPS regardless of the arterial/venous nature of the thrombosis compared with HCs, which was similar to the results of our study." (PMID 34489952, 2021). "CXCL12 levels were higher in the urine of patients with TAPS than in those with OAPS (p=0.0350), APL carriers (p=0.0008), patients with miscarriages (p<0.0001), patients with thrombosis (p<0.0001), patients with RA (p=0.0012), patients with SLE (p<0.0001), and HCs (p<0.0001)." (PMID 34489952, 2021).
brain injury (8 papers, 2005 to 2023). Acute and chronic (see also brain INJURIES, CHRONIC) injuries to the brain, including the cerebral hemispheres, CEREBELLUM, and brain STEM. "But the administered dose range was in a sharp contrast to the reported secreted levels of endogenous CXCL12 in brain injuries, which falls within the ranges of tens to hundreds of picogram per milliliter or milligram." (PMID 24771246, 2015). "Ackr3 is considered a scavenger of the CXC chemokine CXCL12, which prevents leukocytes from entering the microvasculature of the brain; thus, upregulation of Ackr3 promotes blood-brain barrier impairment and inflammatory brain injury." (PMID 34595206, 2021).
depression (8 papers, 2015 to 2025). "In the TST, overexpression of CXCL12 reversed the extended duration of immobility, ameliorating depression-like behavior." (PMID 38129829, 2023). "CCL2 and CXCL12 are chemokines involved in the RSD model of depression, characterised by increased inflammation and glucocorticoid resistance." (PMID 32699209, 2020). "In this figure, chemokines (e.g., CX3CL1, CXCL12, CCL5) with direct neurotransmitter-like or neuromodulatory actions may directly influence neurotransmitter systems that are implicated in depression." (PMID 26441528, 2015). "The aim of this study was to test the relationship between depression and plasma concentrations of CCL2, CCL11, CX3CL1 and CXCL12 in mildly and moderately depressed primary-care patients, as well as the potential influence of an effective iCBT intervention on those molecules." (PMID 31974503, 2020). "Considering that CXCL12, CX3CL1 and their receptors play a crucial role in brain homeostasis and the course of pathological conditions, e.g., neuroinflammation, disturbances in these molecules expression, have been proposed as a potential background of brain disorders, including depression." (PMID 29163165, 2017).
diffuse large B-cell lymphoma (8 papers, 2018 to 2025). "Moreover, leukotriene B4 with CXCL12 synergistically induces the migration of lymphoma cells to the lymph node in DLBCL (diffused large B-cell lymphoma)." (PMID 40076826, 2025). "Here, we propose a model of how ACKR3 controls the migration of the diffused large B-cell lymphoma VAL cells in vitro and in vivo in response to CXCL12." (PMID 36713377, 2022). "The CXCL12/CXCR4 pathway is involved in several aspects of tumor pathogenesis, promoting tumor vasculogenesis and angiogenesis in tumor stem-like glioma cells or regulating lymphoid tumor microenvironment in diffuse large B-cell lymphoma (DLBCL)." (PMID 39273392, 2024).